NUDCD2 (NudC domain containing 2)
Description:
May regulate the LIS1/dynein pathway by stabilizing LIS1 with Hsp90 chaperone.
Synonyms: DKFZp686E10109; NudCL2
Tractability: PROTAC: ubiquitination databases record sites on it; its protein half-life has been measured.
Gene: Protein-coding gene on chromosome 5 (163,446,526 to 163,460,404, reverse strand). Ensembl gene ENSG00000170584.
Subcellular location: Chromosome, centromere, kinetochore; Cytoplasm, cytoskeleton, microtubule organizing center, centrosome; Cytoplasm, cytoskeleton, spindle pole
Subcellular location (Human Protein Atlas): Microtubules; Cytokinetic bridge; Cytosol; Mitotic spindle
Gene Ontology:
Molecular function: protein binding
Cellular component: microtubule cytoskeleton; mitotic spindle; centrosome; spindle pole
Genetic constraint (gnomAD): Loss-of-function variants: 11 observed, 15.41 expected, observed/expected ratio (o/e) 0.71, 90% interval 0.45 to 1.18. The upper end of that interval is the gene's LOEUF score, 1.18, which puts it in group 5 of 6, group 1 being the genes least tolerant of losing a copy. Missense variants: 150 observed, 151.58 expected, observed/expected ratio (o/e) 0.99, 90% interval 0.87 to 1.13. Synonymous variants: 70 observed, 59.54 expected, observed/expected ratio (o/e) 1.18, 90% interval 0.97 to 1.43.
Homologues: Orthologues: chimpanzee NUDCD2 (100% identical), macaque NUDCD2 (100% identical), dog NUDCD2 (99% identical), guinea pig NUDCD2 (99% identical), mouse Nudcd2 (99% identical), rabbit NUDCD2 (98% identical), pig NUDCD2 (94% identical), rat Nudcd2 (93% identical), tropical clawed frog nudcd2 (76% identical), zebrafish nudcd2 (70% identical). Paralogues in human: NUDCD3 (26% identical), NUDC (24% identical).
Diseases named in the same sentence as NUDCD2 in open-access papers:
NUDCD2 is named in the same sentence as 4 diseases in open-access papers, as found by Europe PMC text mining. Sharing a sentence is not in itself a finding about the gene and the disease. The quoted sentences say what the papers report.
viral infection (1 paper, 2022). "Interestingly, we found that the ubiquitination of many host proteins that interact with SARS-CoV-2 was also changed after viral infection, such as ZDHHC5, BUD31, SCP2, ARL6IP4, and NUDCD2, which were reported to interact with the SARS-CoV-2 Spike protein." (PMID 36071039, 2022).
cancer (1 paper, 2022). A tumor composed of atypical neoplastic, often pleomorphic cells that invade other tissues. "And some identified 3′-UTR piSNV-affected genes, such as SLC6A11, NUDCD2, CTNNA3, RAB3C, and AJAP1, are well-studied cancer/disease related genes with a high deleterious mutation rate." (PMID 35654793, 2022).
NUDCD2 also shares sentences with these, for which no sentence is quoted: Lissencephaly (1 paper); tumour (1).